IDE (insulin degrading enzyme)
Diseases named in the same sentence as IDE in open-access papers (continued):
Sharing a sentence is not in itself a finding about the gene and the disease.
type 2 diabetes (47 papers, 2009 to 2026). "IDE has been implicated in the pathogenesis of type 2 diabetes but its role in different tissues involved in glucose homeostasis has only recently begun to be elucidated." (PMID 35652923, 2022). "IDE is a zinc-metallopeptidase which has been implicated in several prevalent diseases including Type 2 diabetes mellitus and AD." (PMID 28219449, 2017). "Human studies suggest that polymorphisms of IDE gene is closely associated with a high risk for type 2 diabetes." (PMID 24740421, 2014). "Meta-analysis of risk associations of CPE rs1583645 and IDE rs6583813 with Type 2 diabetes (T2D) using data from de novo genotyping and in silico analysis in a multi-ethnic population." (PMID 23776430, 2013). "Genome-wide association studies (GWAS) in populations of European ancestry have mapped a type 2 diabetes susceptibility region to chromosome 10q23.33 containing IDE, KIF11 and HHEX genes (IDE-KIF11-HHEX), which has also been replicated in Chinese populations." (PMID 22506066, 2012). "The defective function of the IDE gene is therefore associated with AD and type 2 diabetes." (PMID 35656316, 2022). "In addition, mice with homozygous deletions of IDE show a marked decrease in insulin degradation, while IDE polymorphisms have been associated with type 2 diabetes in humans." (PMID 21731629, 2011). "Hepatic ablation of IDE in knock‐out mouse models produces HI and glucose intolerance, whereas in obese humans, reduction of IDE activity aggravates the HI and facilitates the onset of type 2 diabetes mellitus." (PMID 40476757, 2025). "Insulin‐degrading enzyme (IDE) is an important gene in studies of the pathophysiology of type 2 diabetes mellitus (T2DM)." (PMID 37515308, 2023). "In this paragraph, we briefly summarize the main evidence of IDE involvement in the pathogenesis of type 2 diabetes mellitus (T2DM) and Alzheimer’s disease (AD), and in the regulation of intracellular proteostasis." (PMID 37892174, 2023). "In vivo, the PPARγ activator rosiglitazone increased the expression level of IDE and decreased Aβ levels in a mixed mouse model of AD and type 2 diabetes and alleviated the spatial learning and recognition impairments in these mice." (PMID 33128835, 2020). "Impairment of the insulin-degrading enzyme (IDE) is associated with obesity and type 2 diabetes mellitus (T2DM)." (PMID 28429777, 2017). "As IDE demonstrates an ability to degrade insulin, amylin, and Aβ, it has been suggested that IDE is a candidate gene for both type 2 diabetes and AD." (PMID 26173052, 2015). "For example, APP interacts with susceptibility genes to type 2 diabetes (LAMA1 and IDE) and genes associated with Parkinson's disease risk including SNCA and MAPT." (PMID 24376773, 2013). "It has been proved that insulin-degrading enzyme (IDE), which can reduce the levels of brain A β and insulin, is associated with AD and type 2 diabetes mellitus." (PMID 22792090, 2012). "This association suggests that the functional significance of these SNPs in type 2 diabetes is relayed through the expression of IDE, which plays a central role in insulin metabolism." (PMID 22584726, 2012). "IDE gene is located on chromosome region 10q23-q25 and exhibits a well-replicated peak of linkage with Type 2 diabetes mellitus (T2DM)." (PMID 22107728, 2011). "Importantly, insulin can modulate the clearance of extracellular Aβ oligomers through regulating the insulin-degrading enzyme (IDE), which represents a key molecular link between AD and type 2 diabetes mellitus (T2DM)." (PMID 36010613, 2022). "IDE dysfunction may be associated with some forms of type 2 diabetes (T2DM), in humans and several single nucleotide polymorphisms in non-coding regions of the IDE gene, are associated with the disease." (PMID 32477265, 2020). "However, in patients with type 2 diabetes, the levels of cyclin G2 are positively correlated with that of insulin-degrading enzyme (IDE)." (PMID 30420966, 2018).
type 2 diabetes (continued). "IDE is a potential drug target in the treatment of type 2 diabetes." (PMID 24740421, 2014). "Therefore, both IDE and HHEX genes are strong candidates as susceptibility genes modulating the pathogenesis of type 2 diabetes." (PMID 22506066, 2012). "IDE dysfunction may lead to age-related glucose tolerance and type 2 diabetes mellitus." (PMID 39908369, 2025). "Insulin degrading enzyme (IDE) is a potential drug target in the treatment of type 2 diabetes (T2D)." (PMID 24740421, 2014). "Knowing that both insulin and amyloid-beta (Aβ) are broken down by the insulin-degrading enzyme (IDE), long-standing insulin resistance particularly centrally goes beyond the development of type 2 diabetes to impair neural and cognitive functions." (PMID 39204160, 2024). "Insulin-degrading enzyme (IDE) is a neutral zinc and thiol-dependent metallopeptidase, for which increasing evidence suggests its dysfunction leads to pathogenesis of type II diabetes." (PMID 33143302, 2020). "In a high-fat diet (HFD)-induced preclinical model of type 2 diabetes, administration of the IDE inhibitor 6bK did not emerge as the main focus of the study." (PMID 40724942, 2025). "Together, targeting IDE is an attractive strategy to prevent AD and type II diabetes but safe and potent drugs are currently lacking." (PMID 30338033, 2018). "Most importantly, our results lead us to conclude that, contrary to various suggestions in the literature, acute inhibition of the catalytic function of IDE is not a generally applicable option to treat type-2 diabetes." (PMID 26394692, 2015).
diabetes (44 papers, 2009 to 2026). "As its name suggests, IDE was originally described as an enzyme implicated in insulin metabolism and therefore of potential significance in diabetes mellitus providing one of a number of links between diabetes and AD." (PMID 25278875, 2014). "Mutations in the IDE gene that result in reduced activity of the enzyme and lead to diabetes in a rat model of T2DM also result in enhanced cerebral deposition of Aβ." (PMID 22654727, 2011). "IDE activators with desirable pharmacokinetic properties may be significant for diabetes, as it is questionable to combat with diabetes or hyperinsulinemia through genetic mutations of IDE gene." (PMID 22355395, 2012). "Thus, IDE deficiency may protect from diabetes both by attenuating beta cell recognition by autoreactive T cells and by triggering an intrinsic regenerative beta cell defense." (PMID 39600694, 2024). "Small molecule inhibitors to insulin-degrading enzyme (IDE) have been previously suggested as a potential treatment for diabetes through their ability to reduce insulin degradation and thus increase insulin activity." (PMID 35350789, 2022). "An inducible L-IDE-KO model of study would also help elucidate the impact of IDE function on insulin sensitivity and glucose homeostasis before and after the onset of diabetes in mouse models of T2DM such as the db/db." (PMID 33477364, 2021). "Although the utility of IDE inhibitors in the treatment of diabetes awaits further investigation, their use in promoting wound healing in diabetic patients seems promising and comparatively uncomplicated." (PMID 33668109, 2021). "Recently, some molecules, which are widely studied in diabetes, have been proved to affect Aβ clearance, including insulin-degrading enzyme (IDE), neprilysin (NEP), receptor for advanced glycation end products (RAGE), and matrix metalloproteinases (MMPs)." (PMID 32377293, 2020). "This prediction ofLT10 peptide as a novel putative IDE-inhibitor suggests its possible role in anti-diabetic treatment since IDE- inhibitors are known to assist treatment of Diabetes mellitus by enhancing insulin signalling." (PMID 25816209, 2015). "Recently, several small molecules that can potently modulate the activity of IDE have been discovered and one shows promise in the treatment of diabetes." (PMID 25636406, 2015). "Inhibiting insulin-degrading enzyme (IDE) has been proposed as a potential therapeutic strategy for the treatment of patients with diabetes." (PMID 26394692, 2015). "Insulin-degrading enzyme (IDE) is also known to have Aβ-degrading properties, and hyperinsulinemia in diabetes mellitus competitively inhibits Aβ degradation." (PMID 25368578, 2014). "In 1949, the discovery of insulin-degrading enzyme (IDE), a protease that breaks down the B chain of the insulin hormone, prompted studies of the potential use of IDE inhibitors (IDEIs) to control insulin levels in animal models of diabetes." (PMID 39714747, 2025). "Potential mechanisms also link diabetes and cognitive impairment including a role of the insulin-degrading enzyme (IDE), degrading amyloid β such that amyloid β aggregates in patients with diabetes and hyperinsulinemia as result of lower availability of the IDE." (PMID 36922645, 2023). "Further research using our approach will increase our understanding regarding the role of IDE in diabetes and may provide novel therapeutic approaches in diabetes and related complications." (PMID 35350789, 2022). "Studies of IDE inhibition have shown that modulating IDE activity could potentially be a new therapeutic strategy for treating diabetes." (PMID 35350789, 2022). "Type I is a diabetes-related insulin deficiency and can occur in the brain of AD patients, while type II is a diabetes-related insulin resistance and other diabetes-related indicator abnormalities, such as abnormal end-glycosylation products and insulin-degrading enzyme abnormalities." (PMID 34220413, 2021).
diabetes (continued). "While interesting, these phenotypic changes may be secondary to the metabolic disturbances in IDE-KO mice, since reduced fertility and impaired sperm quality is a known consequence of diabetes." (PMID 33477364, 2021). "Thus, even if IDE inhibitors do prove to have beneficial effects on certain diabetes-related endpoints, it will be important to thoroughly investigate their effects on all organs as well as to assess their potential to influence risk for certain diseases." (PMID 33668109, 2021). "Since IDE- inhibitors are known to assist treatment of Diabetes mellitus by enhancing insulin signalling; our analysis suggest that LT10 peptide might exhibit this novel mode of anti-diabetic activity apart from its known anti-lethal activity." (PMID 25816209, 2015). "As the major insulin-degrading protease, IDE is a candidate drug target in diabetes." (PMID 26394692, 2015). "Additionally, the locus for this gene includes IDE, or insulin degrading enzyme, which would be a stronger candidate for a gene affecting diabetes initially." (PMID 23840313, 2013). "Furthermore, our results lend new support to the old idea that pharmacological inhibition of IDE may represent an attractive approach to the treatment of diabetes mellitus." (PMID 20498699, 2010). "Interestingly, one such impaired enzyme system in diabetes-induced murine models were amyloid-beta degrading enzymes, namely, endothelin-converting enzyme 1 (ECE-1) and insulin-degrading enzyme (IDE)." (PMID 38255204, 2024). "However, modulating IDE activity is not just an area of interest; it is a promising treatment strategy for both diabetes and AD." (PMID 40724942, 2025). "We have previously shown that deficiency for insulin-degrading enzyme (IDE), a ubiquitous cytosolic protease with very high affinity for insulin, induces endoplasmic reticulum (ER) stress and proliferation in islet cells and protects non-obese diabetic mice (NOD) from diabetes." (PMID 39600694, 2024).
Insulin resistance (40 papers, 2008 to 2025). Increased resistance towards insulin, that is, diminished effectiveness of insulin in reducing blood glucose levels. "The importance of IDE in AD is well established as IDE is the only known enzyme that degrades β-amyloid proteins, which are a major cause of AD pathology, and that degrades used insulin which is the cause of insulin resistance." (PMID 28070499, 2017). "The association between insulin resistance and poor cognitive functioning may involve insulin-degrading enzyme (IDE), which plays a role in both insulin and β-amyloid metabolism." (PMID 22611388, 2012). "Liver-specific IDE knockout (L-IDE-KO) mice exhibit insulin resistance and glucose intolerance despite normal insulin levels and preserved β-cell function." (PMID 40724942, 2025). "Insulin resistance reduces the level of insulin-degrading enzyme (IDE) which metabolizes mitochondrial β-amyloids." (PMID 38457008, 2024). "Insulin resistance is characterized by hyperinsulinemia and decreased expression of insulin-degrading enzyme (IDE)–Zn-metalloprotease, which is responsible for cleavage of insulin, amylin, and Aβ." (PMID 37895336, 2023). "Aβ itself can be degraded by a variety of peptidases, including insulin degrading enzyme (IDE), which represents the further relation between hyperinsulinemia, insulin resistance, and AD." (PMID 36834741, 2023). "As other mechanisms, insulin-degrading enzyme, insulin resistance, and acylated glucagon-like peptide 1 (GLP-1) analog have been proposed to link DM and AD, and the role of APOE4 between them is being investigated." (PMID 36466611, 2022). "Resveratrol and EGCG were also found to enhance the activity of insulin-degrading enzyme (IDE) to decompose extracellular Aβ in neurons, and promote its clearance in hyperinsulinemia caused by insulin resistance." (PMID 36430365, 2022). "HFD-induced brain insulin resistance decreased insulin clearance and insulin-degrading enzyme (IDE) levels significantly after geraniol supplementation." (PMID 36304965, 2022). "Conversely, liver-specific IDE knockout (L-IDE-KO) mice fed a high-fat diet (HFD) showed insulin resistance and glucose intolerance accompanied by elevated fasting insulin levels." (PMID 35017319, 2022). "In this context, insulin resistance was revealed to promote Aβ secretion and to halt its clearance by decreasing the production of insulin degrading enzyme (IDE), a key enzyme for Aβ degradation, and competing with Aβ for IDE." (PMID 34366841, 2021). "This statement is supported by a study reporting that induction of insulin resistance in Tg2576 mice reduced the amount and activity of insulin-degrading enzyme (IDE), contributing to an increase in Aβ levels in the hippocampus and cerebral cortex." (PMID 32138327, 2020). "A significant linkage between diabetes mellitus, insulin resistance, and alteration in acetylcholine, apolipoproteins, amylin, and insulin-degrading enzyme were established in various studies." (PMID 32864980, 2020). "Insulin-degrading enzyme insulinase was obtained from the liver extract and found to be responsible for the development of Alzheimer in insulin resistance/diabetic individuals." (PMID 32864980, 2020). "In Tg2576 mice, a high-fat-high-sugar diet induced insulin resistance, decreased central insulin receptor-mediated signal transduction and expression, and decreased the activity of insulin degrading enzyme (IDE)." (PMID 29706884, 2018). "Diet-induced insulin resistance also accelerated Aβ pathology by activating γ-secretase and inactivating insulin-degrading enzyme in the Tg2576 AD mouse model." (PMID 27809235, 2016). "However, impaired insulin signaling and insulin resistance made the expression of insulin degrading enzyme (IDE) reduced in brain, which is a significant contributor to Aβ degradation." (PMID 36313287, 2022).
Insulin resistance (continued). "It was suggested that insulin resistance may contribute to amyloidosis by interfering with insulin degrading enzyme (IDE) mediated degradation of amyloid Aβ peptides." (PMID 26576191, 2015). "Given the proposed link between insulin resistance and AD as a result of insulin degrading enzyme (IDE), RFX3 may be an interesting transcription factor to examine in the context of LOAD pathogenesis." (PMID 24743338, 2014). "IDE gene mutation is responsible for hyperinsulinemia and insulin resistance in the Goto–Kakizaki rats (a genetic model of non-insulin-dependent diabetes)." (PMID 24740421, 2014). "Insulin resistance was also associated with enhanced tau phosphorylation in the ZDF rat T2D model and impairment of the clearance of β-amyloid and phosphorylated tau proteins owing to reduced activity of the insulin-degrading enzyme (IDE), which also degrades β-amyloid." (PMID 38279738, 2024). "Reversion to the ND improved insulin resistance and lipid profile, besides brain-derived neurotrophic factor (BDNF), glycogen synthase kinase-3 beta (GSK3β), and insulin-degrading enzyme (IDE) levels." (PMID 39204160, 2024). "In addition to the adaptive increase of blood adiponectin level, insulin resistance or compromised insulin receptor signaling pathway may downregulate expression of insulin degrading enzyme (IDE), a downstream target of the pathway and protease that digests Aβ as well as insulin." (PMID 37191420, 2023). "In fact, HP-EVOO improved insulin sensitivity in obese rats on an HFD, as manifested by a decrease in the insulin resistance index and the homeostatic model assessment for insulin resistance (HOMA-IR) and an increase in activity of the insulin degrading enzyme (IDE) in the liver." (PMID 40136590, 2025). "Insulin resistance causes over-activation of BACE1 in the brain, which not only causes increased production of amyloid beta plaques but also lowers the activity of insulin-degrading enzyme (IDE) to remove Aβ effectively." (PMID 41003796, 2025). "Insulin resistance in the brain, mimicking peripheral insulin resistance in T2DM, can result in hyperinsulinemia in the brain, creating an environment in which insulin competes with Aβ as a substrate for insulin-degrading enzyme (IDE)." (PMID 38255204, 2024). "Importantly, decreased insulin degrading enzyme (IDE) levels can lead to hyperinsulinemia, which may contribute to insulin resistance." (PMID 35455074, 2022). "Insulin resistance increases key enzymes that produce Aβ and phosphorylate tau, such as BACE1, γ-secretase and GSK3 β, while it reduces levels of key enzymes that degrade Aβ, such as IDE, accompanied by oxidative stress, which damages synaptic remodeling and ultimately leads to memory impairment." (PMID 31178714, 2019). "IDE malfunction contributes to insulin resistance and hyperglycemia in many cases although not all." (PMID 24740421, 2014).